HSD17B4 (hydroxysteroid 17-beta dehydrogenase 4)
Diseases named in the same sentence as HSD17B4 in open-access papers (continued):
Sharing a sentence is not in itself a finding about the gene and the disease.
Zellweger syndrome (3 papers, 2019 to 2024). "Hsd17b4, with its unique three-domain structure and localization in cellular peroxisomes, is involved in fatty acid metabolism, and mutations in its gene may lead to Zellweger syndrome." (PMID 38396857, 2024).
adrenocortical carcinoma (2 papers, 2017 to 2023). "In adrenocortical carcinoma (ACC) the overexpression of HSD17B4 had an average ∼50 days longer OS than patients without." (PMID 36674737, 2023). "Overexpression of HSD17B4 exerted tumor suppressive function in adrenocortical carcinoma and was not related to hormone excess." (PMID 29383116, 2017).
liver cancer (2 papers, 2020 to 2024). An epithelial or non-epithelial malignant neoplasm that arises from the liver. "Consistent with its positive correlation with inflammation in liver cancer tissues, here, its significant correlations with the immune cell infiltrations and immunomodulator gene expressions were obvious in NSCLC, indicating the important roles of HSD17B4 in immune response regulation." (PMID 32265992, 2020).
lung carcinoma (2 papers, 2020 to 2023). "Further, through thousands of protein screenings, we identified four proteins (MYH9, GNB1, ALOX12B, HSD17B4) that can predict the response to MET inhibitors for MET-dysregulated lung cancer patients." (PMID 36612298, 2023). "Considering the important roles of immune dysfunction during lung cancer occurrence and progression, the potential effects of HSD17B4 in immunoregulation might provide new clues for NSCLC immunotherapy." (PMID 32265992, 2020). "Notably, considering the importance of HSD17B4 and ACAA1 in peroxisomal β-oxidation of very long fatty acids, the dysfunction of the process in NSCLC was indicated, consistent with the anti-tumor function of β-oxidation in lung cancer in a previous study." (PMID 32265992, 2020).
non-small cell lung carcinoma (2 papers, 2020 to 2024). A group of at least three distinct histological types of lung cancer, including non-small cell squamous cell carcinoma, adenocarcinoma, and large cell carcinoma. "HSD17B4 downregulation was also shown to be clinically significant in non-small-cell lung cancer." (PMID 39038933, 2024).
polycystic ovarian syndrome (2 papers, 2017 to 2024). "HSD17B4 was also mentioned as a potential therapeutic target in polycystic ovarian syndrome and BC." (PMID 39038933, 2024).
amyotrophic lateral sclerosis (1 paper, 2024). Amyotrophic lateral sclerosis (ALS) is a neurodegenerative disease characterized by progressive muscular paralysis reflecting degeneration of motor neurons in the primary motor cortex, corticospinal tracts, brainstem and spinal cord. "A more comprehensive analysis indicates that upregulated proteins (ELOVL5, ELOVL7, TECR, HSD17B4, ACSL1, HACD2, and CBR4) are significantly enriched within the pathways of oxidative phosphorylation and metabolic pathways pertinent to amyotrophic lateral sclerosis." (PMID 39335340, 2024).
autism spectrum disorder (1 paper, 2024). A spectrum of developmental disorders that includes autism, and Asperger syndrome. "Previous reports suggest a correlation between alterations in the HSD17B4 gene and autism spectrum disorders." (PMID 38539661, 2024).
Cerebral atrophy (1 paper, 2022). Atrophy (wasting, decrease in size of cells or tissue) affecting the cerebrum. "HSD17B4 has been reported to play an important role in the catalyzing β oxidation of very long chain fatty acids (VLCFA), and mutations in this gene can cause progressive cerebral atrophy in clinical cases." (PMID 35847024, 2022).
cerebrotendinous xanthomatosis (1 paper, 2025). Cerebrotendinous xanthomatosis (CTX) is an anomaly of bile acid synthesis characterized by neonatal cholestasis, childhood-onset cataract, adolescent to young adult-onset tendon xanthomata, and brain xanthomata with adult-onset neurologic dysfunction. "Among Rajput caste, seven RGDs were caste-specific including Cerebrotendinous Xanthomatosis, congenital diarrheal syndrome, HSD17B4-related disorder, hypercholesterolemia type B, Menke-Hennekam Syndrome, RAG1-associated disorder and Sjögren-Larsson Syndrome." (PMID 41516090, 2025).
chordoma (1 paper, 2013). Chordomas are rare malignant tumors arising from embryonic remnants of the notochord in axial skeleton. "By comparing methylation patterns of blood from healthy individuals and chordoma patients we found 20 significantly differentially methylated genes; 15 hypermethylated in chordoma (for example RASSF1, KL, RARB, HIC1, and FMR1) and 5 hypomethylated (HSD17B4, BAZIA, STAT1, NEUROGL, and JUP)." (PMID 23533570, 2013).
colon cancers (1 paper, 2023). "Furthermore, increased expression of HSD17B4 was correlated with poorer prognosis in patients with prostate, breast, and colon cancers." (PMID 37108962, 2023).
congenital cardiomyopathy (1 paper, 2025). "Under normal conditions, FGF21 loss had minimal effects on most cardiac FAO genes, except peroxisomal Ehhadh, Hsd17b4, and ER-residing Hacd1/2 (linked to congenital cardiomyopathy)." (PMID 40998786, 2025).
developmental delay (1 paper, 2020). "Recessive mutations in the HSD17B4 gene are known to cause DBP-deficiency, an early-onset neurological disorder characterized by neonatal hypotonia, seizures, visual impairment, global developmental delay, and typical biochemical profile." (PMID 32904102, 2020).
diabetes (1 paper, 2015). "In addition, it uncovers biomarker genes such as ACAA1 and HSD17b4 which could be further probed in future studies of pre-diabetes and T2D." (PMID 25784953, 2015).
Infertility (1 paper, 2014). "Our case expands the phenotypic spectrum of HSD17B4-deficiency, representing the first male case reported with infertility." (PMID 24602372, 2014).
ovarian tumours (1 paper, 2023). "In addition, increased expression of the E1 synthetic enzymes HSD17B2, HSD17B4 and HSD17B6 in ovarian tumours is inversely associated with the probability of PPS (HR = 1.21 (1–1.45), p = 0.045; HR = 1.29 (1.07–1.55), p = 0.0073; respectively)." (PMID 36674737, 2023). "Moreover, elevated intratumoural E1 synthesis by HSD17B2, HSD17B4, HSD17B6 and HSD17B14 overexpression in primary ovarian tumours correlate with lower OS." (PMID 36674737, 2023).
schizophrenia (1 paper, 2025). A major psychotic disorder characterized by abnormalities in the perception or expression of reality. "Interestingly, we identified genes associated with fatty acid metabolism amongst VMPs with concordant changes in blood and brain, including HSD17B4, CYP4V2, FADS2, and SCD, indicating altered DNA methylation variance may impact fatty acid metabolism in these tissues in schizophrenia." (PMID 39271751, 2025).
seminoma (1 paper, 2025). A radiosensitive malignant germ cell tumor found in the testis (especially undescended), and extragonadal sites (anterior mediastinum and pineal gland). "The polymorphism of HSD17B4 and CYOP1A1 genes might increase the likelihood of developing TGCT, particularly seminoma over NSGCT." (PMID 40011822, 2025).
small cell carcinoma (1 paper, 2017). A neuroendocrine carcinoma composed of small malignant cells which are often said to resemble "oat cells" under the microscope. "Constitutive level of HSD17B4 was studied in 2 cell lines, in which NCI-H295R is ACC cells and SW13 is small cell carcinoma of adrenal cortex." (PMID 29383116, 2017).
type 2 diabetes (1 paper, 2013). "The seven loci shed new light on regions containing genes with a reported role for type 2 diabetes (PPARG, ADAMTS9, VEGFA), lipids (GRB14, MAP3K1) and hormone metabolism (HSD17B4)." (PMID 23754948, 2013).
cancer (16 papers, 2017 to 2025). A tumor composed of atypical neoplastic, often pleomorphic cells that invade other tissues. "Previous studies showed that HSD17B4 was highly expressed in most human cancers and was significantly associated with treatment efficacy." (PMID 36612298, 2023). "HSD17B4 emerges as highly selective across multiple cancer cell lines and specifically BC (DepMap Public 23Q4 + Score, Chronos gene-affect score)." (PMID 39038933, 2024). "In the last decade, HSD17B4 has been reported to be involved in the tumorigenesis and progression of many cancers by promoting estrone production, which is subsequently metabolized into carcinogenic 4-OH or 16α-OH estrone metabolites." (PMID 37108962, 2023). "Previous results have reported that hsd17b4 is a multiple-function enzyme involved in the progression of various cancers." (PMID 37904220, 2023). "We also analyzed cancer samples during neoadjuvant chemotherapy for HSD17B4 methylation, Ki-67 index and tumor size to monitor response to the therapy." (PMID 32968149, 2020). "Previous results have reported that HSD17B4 is a multiple-function enzyme involved in the progression of various cancers, including PCa." (PMID 32678070, 2020). "HSD17B4 methylation levels were very low in almost all cancer cell lines, and its expression levels were very high in them." (PMID 32968149, 2020). "To explore the function of HSD17B4 in cancer cells, we knocked down endogenous HSD17B4 by shRNA or overexpressed exogenous Flag-HSD17B4 in PCa cells and detected a significant difference in the proliferating velocity and colony formation." (PMID 32678070, 2020). "The vast majority of cancer cell lines highly express HSD17B4, thereby suggesting that HSD17B4 expression is essential for the survival of most cancer cell lines." (PMID 32968149, 2020). "The use of such a marker will enable us to assess HSD17B4 methylation levels and cancer cell fractions in the same DNA samples, and accuracy of methylation levels in cancer cells will increase." (PMID 28186977, 2017). "Interestingly, the post-translational regulation of HSD17B4 stability through acetylation at lysine 669—modulated by sirtuin 3 (SIRT3) and CREB-binding protein (CREBBP) —provides a potential mechanism for fine-tuning HSD17B4 activity in the context of cancer." (PMID 40647540, 2025). "This indicated that cancer cells with HSD17B4 methylation were preferentially killed by the treatment, and that HSD17B4 methylation may also be useful as a response marker for treatment." (PMID 32968149, 2020). "Therefore, we compared the powers of change of HSD17B4 methylation and the Ki-67 index in cancer samples during treatment to predict a final response, namely as a response marker." (PMID 32968149, 2020). "Also, our findings that genetic manipulation of HSD17B4 did not alter cell motility in SW13 cells, indicating that effect of HSD17B4 is cell- and cancer- context dependent and constitutive HSD17B4 expression is important for its function." (PMID 29383116, 2017). "Expressional differences of HSD17B4, ACAA1, and PXMP4 between NSCLC cell lines with different anti-cancer drug sensitivity." (PMID 32265992, 2020). "The HSD17B4 methylation level consistently decreased in cancer samples that achieved pCR, while not consistently in cancer samples that did not achieve pCR." (PMID 32968149, 2020). "Unlike Ki-67 index and tumor size, HSD17B4 methylation decreased consistently in cancer samples that achieved pCR." (PMID 32968149, 2020). "In our study, however, HSD17B4 appears to play a tumor-suppressive role in ACC, and the effect was even cancer type restricted as the results we received using NCI-H295R cells could be only in part repeated in SW13 cells, which is not de facto ACC." (PMID 29383116, 2017). "However, only HSD17B4 overexpression induced increased G1 population in SW13 cells and KD did not, indicating an inherent difference between the cancer types." (PMID 29383116, 2017).
tumor (16 papers, 2013 to 2025). "MYH9, GNB1, and ALOX12B were negatively associated with the tumor response, which represented biomarkers of poor outcomes, while HSD17B4 was positively associated with the tumor response." (PMID 36612298, 2023). "HSD17B4 plays a role in immune regulation and tumor progression, which is positively correlated with immune cell infiltration in LUAD." (PMID 40722386, 2025). "VK2 not only inhibited the tumor growth on nude mice bearing HepG2 cells but also suppressed the proliferation of HepG2 cells by inducing HSD17B4 expression." (PMID 34858832, 2021). "In our experiment, it was proved that the expression of HSD17B4 was elevated in HCC patients, and the high expression of HSD17B4 promoted tumor proliferation." (PMID 34858832, 2021). "We measured the effect of HSD17B4 on the growth of transplanted tumor and the inhibitory effect of VK2." (PMID 34858832, 2021). "In most samples, the levels of total HSD17B4 protein were higher in the tumor tissues compared with levels in the normal prostate tissues." (PMID 32678070, 2020). "Statistical analysis of quantified images indicated that the differences in HSD17B4 protein levels (P < 0.001) and in Ki-67 protein levels (P < 0.001) between tumor and normal tissues are all significant." (PMID 32678070, 2020). "In most samples, the levels of both HSD17B4 and Ki-67 protein were higher in the tumor tissues compared with levels in the normal prostate tissues." (PMID 32678070, 2020). "Compared with the normal prostate tissues, the levels of total HSD17B4 were higher and the levels of relative K669-acetylated HSD17B4 were lower in the tumor tissues." (PMID 32678070, 2020). "In further in vitro studies, where micro- and macro- environments were much simpler, the tumor suppressive role of HSD17B4 was amplified." (PMID 29383116, 2017). "Multivariate analysis, including tumor stage and hormone receptor status, showed that HSD17B4 methylation was an independent predictive factor (odds ratio: 10.0, 95% confidence interval 2.54–39.50, P = 0.001)." (PMID 28186977, 2017). "In the in vivo study, we observed significantly increased tumor growth in NCI-H295R cell with HSD17B4 KD." (PMID 29383116, 2017). "Given that excessive hormone is immunosuppressive and the effect of HSD17B4 can be, in a way, tumor suppressive by modulating hormone level." (PMID 29383116, 2017). "However, in the GSE32879 dataset, only seven genes (APOA2, CAT, ACOX1, APOE4, AGXT, EHHADH, HSD17B4) were observed to be significantly reduced in tumor samples." (PMID 38274331, 2024). "Statistical analyses of quantified images indicated that the differences in total HSD17B4 protein levels (P < 0.001), in K669-acetylated HSD17B4 (P < 0.001), and in the ratio of K669-acetylated HSD17B4 versus total HSD17B4 proteins (P < 0.001) between tumor and normal tissues are all significant." (PMID 32678070, 2020). "Thus, the results exhibited that VK2 can inhibit the tumor growth by HSD17B4 overexpression." (PMID 34858832, 2021). "However, considering the differences in their prognostic effects, regulations, correlations with tumor purity and immune infiltrations effects between the two subtypes, further study is needed to investigate the specific functions of HSD17B4, ACAA1, and PXMP4 in LUSC and LUAD, respectively." (PMID 32265992, 2020). "In tumor samples taken from the GSE45001 and GSE32879 datasets, seven genes (APOA2, CAT, ACOX1, APOE4, AGXT, EHHADH, and HSD17B4) showed a substantial downregulation." (PMID 38274331, 2024). "Here, similar to HSD17B4, ACAA1 was also found to be down-regulated and negatively correlated with MKI67 expression in NSCLC, indicating its anti-tumor potential." (PMID 32265992, 2020).
tumor (continued). "Through Oncomine, Human Protein Atlas (HPA) and the Clinical Proteomic Tumor Analysis Consortium (CPTAC), three K-DEPGs (HSD17B4, ACAA1, and PXMP4) were confirmed to be down-regulated in NSCLC at both mRNA and protein level." (PMID 32265992, 2020). "For instance, the methylation of progesterone receptor (PGR), hydroxysteroid 17-beta dehydrogenase 4 (HSD17B4), and cadherin 13 (CDH13) genes in both HER2 positive BCAFs and tumour cells was found to enhanced BC progression and invasion." (PMID 33066013, 2020). "HSD17B4, ACAA1, and PXMP4 were all strong expressed in lung (pneumocytes) while there was a negative to moderate expression of HSD17B4 and ACAA1 in the cytoplasm or membrane of LUSC and LUAD tumor cells." (PMID 32265992, 2020).
genetic disease (2 papers, 2019). "For the D-bifunctional enzyme (HSD17B4) which is associated with severe genetic disease, inactivation of the PTS1 creates a purely cytosolic enzyme that cannot exert its peroxisomal function of fatty acid degradation and bile acid side chain shortening." (PMID 31533369, 2019).
adenocarcinoma (1 paper, 2023). A common cancer characterized by the presence of malignant glandular cells. "In 230 patients with adenocarcinoma from the TCGA cohort, higher expressions of MYH9, GNB1, and ALOX12B were associated with poor overall survival outcomes, while higher expression of HSD17B4 was associated with better survival outcomes." (PMID 36612298, 2023).
HSD17B4 also shares sentences with these, for which no sentence is quoted: retinopathy (5 papers); retinal degeneration (4); neurological disorder (3); hearing loss (2); infantile Refsum disease (2); peripheral neuropathy (2); Refsum disease (2); age-related macular degeneration (1); bladder cancer (1); Blindness (1); cardiovascular disease (1); cartilage-hair hypoplasia (1); cataract (1); cerebellar ataxia (1); Cerebellar atrophy (1); deafness (1); diabetic retinopathy (1); Dystonia (1); epilepsy (1); fatty acid metabolic disorder (1); female infertility (1); glioma (1); infection (1); Intellectual disability (1); liver steatosis (1); lymphoblastic leukemia (1); male infertility (1); Menke-Hennekam syndrome (1); metabolic disorder (1); mitochondrial disease (1).
A further 14 diseases each share a sentence with HSD17B4 in 1 paper.